CD4 (CD4 molecule)
Diseases named in the same sentence as CD4 in open-access papers (continued):
Sharing a sentence is not in itself a finding about the gene and the disease.
influenza (continued). "The effector CD4+ and CD8+ T cells generated after the booster immunization are expected to include influenza-specific T cells that could provide a rapid response to clear the pathogen." (PMID 37197659, 2023). "Though the biological relevance of this finding is unknown, we previously showed that specific CD4 responses to influenza A(H1N1) correlate with SARS-CoV-2 specific CD4 T-cells, suggesting a protective effect of pre-existing influenza specific T-cells." (PMID 36845120, 2023). "Furthermore, we demonstrated that, on the 10th day of infection, the proportions of CD4+ TM and CD8+ TM cells were significantly increased, which meant that a stable TCM and TEM lineage was established in the early stage of influenza infection." (PMID 37828468, 2023). "In influenza infection, CXCR3 is important for promoting T follicular helper (TFH) cell activity and antibody production, and in mouse TB models it is a marker for a protective antigen-specific CD4+ T cell subset." (PMID 37896952, 2023). "However, and in contrast to CD4+ T cells, the CD8+ T cells recruited are less numerous compared to influenza." (PMID 37696824, 2023). "has been shown to induce improved IgG, CD4+ and CD8+ T-cell responses, uptake of NP antigens into dendritic cells, broad protection against H1N1 and H3N2 lethal challenges in mice and can be used with inactivated influenza vaccines to increase protection." (PMID 35663997, 2022). "Importantly, this study also showed that ustekinumab did not impair cellular immune responses, as assessed by the proliferation of influenza-specific CD3+, CD4+, and CD8+ T cells." (PMID 35214755, 2022). "CD4 CTL have been mostly reported in chronic viral infections such as human cytomegalovirus and human immunodeficiency virus, but also in acute infections such as influenza when CD8 responses were impaired." (PMID 36798517, 2022). "Comparable levels of CD4+ and CD8+ T-cells were seen as in the earlier phase I trials, but the vaccine regimen was unable to decrease total viral shedding, symptom score, or the incidence of influenza-like illness after infection." (PMID 36052083, 2022). "Similarly, severe influenza disease is characterised by increased inflammatory cytokines and diminished influenza-specific responses from CD8+ T cells, CD4+ T cells, NK cells, MAIT cells, γδ T cells and antibody secreting cells (ASC)." (PMID 35603215, 2022). "Therefore, significantly decreased expression of CD28, CD40L, IL12R, and CD69 in obese subjects leads to markedly lower activation of CD4+ and CD8+ T cells after influenza vaccination." (PMID 36295052, 2022). "The microbiota-host interactions have been shown to modulate the host immune responses to Influenza and SARS-CoV-2 infection, wherein the active commensal microbes are involved in the generation of virus-specific CD4 and CD8 T-cells following the influenza virus infection." (PMID 36532032, 2022). "Indeed, CD4 and CD8 T cells show age-related changes in function, with changes in CD4 T cells during aging influencing both CD8 T function and B cell antibody production in response to influenza." (PMID 35821836, 2022). "Independent of IFN-γ secretion, CD4+ T cell cytotoxicity has been demonstrated during viral infection, particularly lethal doses of influenza." (PMID 35880171, 2022). "Apart from CD8+ T cells, we also identified influenza-specific CD4+ T cells in 5/5 H3N2-infected patients with either HLA-DR*01:01-, DR*04:01- or DR*11:01-HA-tetramers, despite ~10-fold lower numbers of antigen-specific CD4+ T cells ex vivo." (PMID 33976217, 2021). "In general, among influenza+ patients, tetramer+CD8+ T cells consisted of central memory-like (Tcm, CD27+CD45RA–) and, to a lesser extent, effector memory-like (Tem, CD27–CD45RA–) phenotypes, while tetramer+CD4+ T cells were predominantly of Tcm-like cells." (PMID 33976217, 2021).
influenza (continued). "iBALTs within the LRT are the primary niches for lung CD4 TRM cells following influenza infection, which is in contrast to those influenza-specific CD8 TRM cells that are primarily localized to the site of regeneration in the lung parenchyma following tissue injury." (PMID 34572004, 2021). "Moreover, there was an increase in CD4+ and CD8+ T cell responses to H1N1, H3N2, and influenza B relative to baseline in those who were vaccinated with Multimeric-001." (PMID 34579269, 2021). "Here, influenza+ patients’ PBMCs were incubated with live seasonal H1N1, H3N2, B/YAM and B/VIC viruses to measure influenza-specific innate (NK, γδ, CD161+TRAV1-2+ or MAIT cells) and adaptive (CD4+ and CD8+ T cells) immune responses elicited via IFN-γ production after 18 h." (PMID 33976217, 2021). "Pneumococcal colonization status did not affect the levels of either influenza-specific IFN-γ–producing CD4+ or TRM IFN-γ–producing CD4+ T cells." (PMID 33497364, 2021). "Adoptive transfer experiments showed that lung-associated CD8+ T-cells following OVX836 vaccination can protect the animals, whereas serum and CD4+ T-cells from immunized mice were not similarly protective in the influenza challenge model." (PMID 34177921, 2021). "Application of influenza vaccine-coated, but not uncoated HD-MAPs was associated with an increase of CD3+, CD4+ and CD8+ T cells as well as CD11c+ DCs in the skin." (PMID 34329337, 2021). "However, the CD4+ T and CD8+ T subsets, and B cells were significantly enriched in normal controls compared with influenza samples." (PMID 33448094, 2021). "Following stimulation with influenza antigens, CD4+ TRM T cells produced TNF-α in all vaccinated groups but not in the unvaccinated group." (PMID 33497364, 2021). "cTfh cells share phenotypic and functional properties to GC Tfh cells, and it has been shown that inactivated influenza vaccination (IIV) induces expansion and PD-1/ICOS-activation of CD4+CXCR5+CXCR3+ cTfh type-1 (cTfh1) cells, which correlated with antibody and CD19+CD27++CD38++ ASC responses." (PMID 33976217, 2021). "We observed that even in the absence of vaccination, healthy adults showed CD4+ T cell responses to influenza stimulation, which likely reflects their lifelong exposure to influenza viruses." (PMID 33497364, 2021). "Others in the field have found that adoptive transfer of TCR transgenic CD4 Trm cells isolated from lung, but not spleen, also mediated protection from influenza challenge." (PMID 34970279, 2021). "Overall, we show an extensive breadth of highly activated, non-cultured, ex vivo influenza-specific memory CD4+ and CD8+ T cells detected during acute IAV infection, which were still present in a less activated state following recovery." (PMID 33976217, 2021). "In order to determine the role of the different immune arms in the protection against lethal influenza challenge following OVX836 vaccination, we performed adoptive transfer of CD8+, CD4+ T-cells, or serum from vaccinated mice into recipient mice prior to influenza challenge." (PMID 34177921, 2021). "In addition, researchers have used antibodies to deplete immune cells, such as CD4, CD8, or NK cells, to study the contribution of these cells to the protection against influenza infection in vaccinated mice." (PMID 34071367, 2021). "Adoptive transfer of HA-pulsed, TRS-treated DCs significantly increased the populations of IFN-γ+CD4+ T cells and IFN-γ+CD8+ T cells in the BALF and decreased the number of live influenza particles in the lung, resulting in an increased survival period and bodyweight of influenza-infected mice." (PMID 33178197, 2020). "Data suggest that while antibody responses, B cells, CD4 and CD8 T cells are all required to optimally clear an influenza infection protect against further infection, transfer of influenza-specific CD4 T cells protects influenza-naïve mice from challenge in the absence of B cells or CD8 T cells." (PMID 32210973, 2020).
influenza (continued). "With the T-cell proliferation, we showed comparable proliferation of influenza-specific CD4+ and CD8+ T cells in all study populations, but the effector functions of CD4+ and CD8+ T cells are still unknown." (PMID 32824111, 2020). "More recently, CD4+ T cells have also been shown to have an important role in clearing influenza infection, with the lack of CD4+ T cells correlating with reduced viral clearance." (PMID 32117155, 2020). "In fact, it was reported that CD4+ T-cells contribute effector inflammation cytokines after acute influenza infections in mice, even after no virus is detectable in blood." (PMID 32752138, 2020). "Importantly, administration of TRS-stimulated DCs upregulated the populations of IFN-γ-secreting CD8+ and CD4+ T cells as well as secretion level of IFN-γ and induced viral clearance in influenza-infected mice." (PMID 33178197, 2020). "Several studies have demonstrated the importance of polyfunctional CD4 + T-cells in the control of influenza in non-transplant patients." (PMID 32572168, 2020). "In severe influenza, the proportion of classical monocytes significantly increased whereas those of DCs, non-EM-like CD4+ T cells, EM-like CD4+ T cells, IgG+ B cells, and IgG- B cells significantly decreased." (PMID 32651212, 2020). "We next assessed influenza-responding T cells by analyzing activated (CD44hi) CD4+ and CD8+ T cells, as well as influenza specific T cells by using MHCII and MHCI tetramers containing influenza A specific peptides to assess CD4+ and CD8+ T cell responses, respectively (Tet+ cells)." (PMID 33373420, 2020). "Respiratory CD4 and CD8 TRM, which are induced by the infection of mice with influenza virus or through i.n. immunization with a live-attenuated virus, mediate protection against challenge with heterosubtypic influenza strains in mice." (PMID 33096737, 2020). "The aim of our study was therefore to evaluate the CD4 + and CD8 + T-cell responses during natural influenza infection in a cohort of SOT patients and to compare it to the T-cell responses elicited by the influenza vaccine in this population." (PMID 32572168, 2020). "While this group found no role for the IL-33-producing ILC2 cells in influenza exacerbation of asthma, another group using the same HDM-sensitized murine model implicated ILC2s as well as CD4 + T cells." (PMID 33101299, 2020). "Indeed, when stimulating with specific peptide epitopes we were able to detect both CD4 and CD8 response in Influenza-infected mice." (PMID 31443439, 2019). "In summary, age-dependent homeostatic dysregulation involving the proliferation of CD4 and CD8 T-cell subsets, including Tregs, seem related to a reduced responsiveness to influenza vaccination as well as to a higher inflammatory status in an elderly population." (PMID 31312227, 2019). "Our goal was to test the protective capacity of memory CD4 T cells against influenza in the absence of any other immune cells primed by the virus, and to determine the mechanisms that these cells employ to combat infection." (PMID 30641955, 2019). "A functional test to assess sensitization of T cells to vaccine antigens in order to estimate the effectiveness of memory T cells was performed by evaluating the expression of an activation surface marker (CD69) on CD4+ and CD8+ T cells following 24h incubation with the influenza vaccine antigens." (PMID 31600331, 2019). "In the context of respiratory viral infection, T-cell-restricted deletion of IL-10 recapitulates the effects of global IL-10 blockade by augmenting Th1-dependent immunopathology during influenza and RSV infections in mice, with both CD4+ and CD8+ T cells producing IL-10 in these models." (PMID 30874596, 2019). "Although CD4 T cell responses to infection with influenza and vaccine development have not received as much attention as the CD8 T cells and humoral responses, their role is still important for host protection against influenza." (PMID 31683888, 2019).
influenza (continued). "Given the multiple functions of CD4 T cells in the anti-influenza immune response and the widespread use of IIV in infants in many countries, including the U.S.37, a better understanding of how early CD4 T cell immunity is established post-vaccination is critical." (PMID 30692574, 2019). "CD4+ T cells are important to support both B and CD8+ T cell function in the lung and have been proposed as potential correlates of vaccine protection against influenza." (PMID 31166987, 2019). "Therefore, a promising universal influenza vaccine needs to stimulate B, CD8, and CD4 T cell responses against various conserved proteins for efficient viral clearance, long-lasting immunity, and prevention of reinfection." (PMID 31683888, 2019). "In contrast, no Perf/GzmB+ events were detected among a coexisting influenza M143–59–specific CD4+ T cells in this donor, or any other patients with IM (n = 5), excluding the possibility of bystander CD4+ T cell activation." (PMID 31308093, 2019). "We extended this testing for CD4 cell recall responses to EBV(P3H3), Measles, Mumps, and Influenza." (PMID 29301355, 2018). "Considering that IAV-infected BMDCs displayed higher maturation in coculture with ILC1s and either CD8 or CD4 T cells, ILC1s might communicate with CD4/CD8 T cells in a DC-dependent manner during influenza infection." (PMID 29623077, 2018). "Second, this study was not powered to assess the impact of CD4+ cell count or ART on influenza incidence and severity." (PMID 29045699, 2018). "The factors that control CD4 T cell homing to the lung after influenza infection are not well defined." (PMID 29681900, 2018). "CD4+ T cells are also essential for robust CD8+ T cells responses, crucial for flu viral clearance." (PMID 29616390, 2018). "We observed that M2e-specific CD4+T cells were dominated by Th17 cells, which conveyed protection against influenza that was independent of anti-M2e-antibodies." (PMID 30271406, 2018). "However, since CD4 and CD8 T cells typically recognize conserved epitopes from internal viral proteins, it is possible that prior exposure to influenza results in the accumulation of TRM cells capable of providing cross strain protection." (PMID 30386342, 2018). "Infected allergen exposed mice had augmented innate and adaptive immune responses, seen in the lung draining lymph nodes (MLN), lungs and airways, which led to the earlier recruitment of CD4 and CD8 T cells, as well as influenza specific CD8 T cells into the lungs." (PMID 29293541, 2018). "Along these lines, secondary effector CD4 T cells responding to influenza in the lung contain both Th17 and TFH subsets, neither of which are present during primary infection." (PMID 30386342, 2018). "Therefore, the obtained data suggest that CD4 T cells engage in a complex interaction with GITR+ ILC1s and regulate ILC1 functionality in the combat against influenza infection." (PMID 29623077, 2018). "Consistent with this, CD4 TRM generated after influenza infection do not express Nur77 at late phases of infection, suggesting that they are no longer receiving TCR mediated signals." (PMID 30386342, 2018). "The immunodominant nature of NP and extensive conservation may make the NP protein a good candidate for stimulating cross-reactive CD4 and CD8 T cell responses to diverse influenza strains." (PMID 29666412, 2018). "In order to investigate whether the main mediator of protection was antibodies or T cells, immunized mice were depleted of CD4+ and CD8+ T cells just prior to a lethal influenza challenge." (PMID 28931687, 2017). "Several publications have showed contradictory results, indicating that CD4+ T cells of patients injected with influenza vaccine had no significant change." (PMID 28694558, 2017). "In addition to MoDCs, we also observed a reduction in the capacity of pDCs from elderly to prime CD4 and CD8 T cell responses after stimulation with influenza." (PMID 28798751, 2017).
influenza (continued). "The requirement for a CD8 T cell epitope in the J-LEAPS vaccine was indicated in studies with influenza vaccines in which attachment of the J-ICBL to CD8 T cell epitopes generated protective immunogens but attachment to CD4 T cell/B cell epitopes did not." (PMID 28459074, 2017). "Here we explored the role that peptide specificity plays in the partitioning of the polyclonal CD4 T cell repertoire between Tfh and NonTfh lineages during the response to influenza." (PMID 27329272, 2016). "In mice, CD4 effectors of multiple subsets including helper type 1 (Th1) cells producing interleukin-2 (IL-2) and IFNγ that recruit virus-specific cytotoxic T lymphocytes (CTL) to the lungs to kill influenza-infected lung epithelial cells." (PMID 26941738, 2016). "Therefore, during uncomplicated influenza, adaptive immune response ultimately results in clearance of IFV from the lungs through the activity of virus-specific antibodies and CD4+ and CD8+ T cells." (PMID 28066442, 2016). "Overall, CD4 T-cell responses in aged individuals are not too dissimilar from those found in young adults following vaccination with an inactivated influenza vaccine." (PMID 26941738, 2016). "It will be interesting to verify if the kinetics, rather than the baseline level, of influenza specific CD4+CD40L+ activated T cells is correlated with the H1N1 serological response." (PMID 26954292, 2016). "Influenza-specific memory CD8+ and CD4+ T-cells are abundantly found following bronchoalveolar lavage of infected patients and healthy adults, although they have a much higher activation threshold compared to peripherally circulating antigen-specific memory T-cells." (PMID 27242800, 2016). "In addition, MCC950 treatment reduced B220+, CD4+ and CD8+ cells, as well as influenza-specific CD8+ T cell numbers." (PMID 27283237, 2016). "As a result, the monospecific CD4 T cell population only recognizes an antigen from influenza not seen under normal conditions, and so any CD4 T helper cells would be unable to provide cognate antigen-specific help to FliC- or DENV-specific B cells." (PMID 26265529, 2015). "We then examined the maintenance of influenza-specific CD4+ T cell memory in oseltamivir and PBS-treated mice after infection and found similar total numbers (p>0.05) of I-AbHA211 and I-AbNP311-specific CD4+ T cells in the MedLN at d40." (PMID 26086392, 2015). "We assessed the correlations between influenza vaccine-specific humoral immunity measures and other overall humoral immune response variables measured over time, and age/immunosenescent markers (TREC, TERT, CD28 expression on CD4+ and CD8+ T cells)." (PMID 25816015, 2015). "In accordance with the multiple functions of CD4+ T cells, it has been shown that mice lacking functional CD4+ T cells suffer more severe influenza infections, and that the development of immunological memory is impaired." (PMID 26257735, 2015). "A large field study found that the majority of subjects with high IFN-γ secreting cells (≥ 100 spot forming cells per million lymphocytes) were protected from influenza infection, but whether these responses were CD8+, CD4+ or NK cells was unclear." (PMID 26343192, 2015). "This phenomenon is not restricted only to influenza, since numerous infectious models have demonstrated the importance of CD4+ T cells in cellular mediated protection." (PMID 25140692, 2014). "For influenza-specific CD8+ T cells, we utilized an MHC class I tetramer specific for H-2Db-resricted epitope of the influenza nucleoprotein (NP, DbNP366-74) of PR/8, and CD4+ Tregs were identified by expression of the transcription factor Foxp3." (PMID 24844920, 2014). "Conversely, anti-CD4 antibody treatment did not affect the severity of influenza-induced lung injury in either IFN-γ−/− or SOCS1−/−IFN-γ−/− mice." (PMID 25500584, 2014).